PRLR (prolactin receptor)
Diseases named in the same sentence as PRLR in open-access papers (continued):
Sharing a sentence is not in itself a finding about the gene and the disease.
lupus (2 papers, 2012 to 2021). "Our aim was to determine if different splenic B cell subsets express the prolactin receptor and if the presence of prolactin influences these B cell subsets and correlates with development of lupus." (PMID 22404893, 2012). "We found that transitional B cells express the prolactin receptor at higher levels compared to mature B cells in C57BL/6 mice and the lupus-prone MRL/lpr and MRL mouse strains." (PMID 22404893, 2012). "We found that all B cell maturation stages in bone marrow express the prolactin receptor long isoform, in both wild-type and MRL/lpr mice, but its expression increased only in the immature B cells of the latter, particularly at the onset of lupus." (PMID 33557010, 2021). "All B cell maturation stages in bone marrow express the prolactin receptor long isoform in both wild-type and MRL/lpr mice, but its expression increased only in the immature B cells of the latter, particularly at the onset of lupus." (PMID 33557010, 2021).
lymph node metastasis (2 papers, 2011 to 2022). "On the basis of the model, we predicted that distant metastasis of tumor, lymph node metastasis, and PRLR expression were the risk factors of unfavorable prognosis." (PMID 36556307, 2022). "To exclude the possibility that the divergent PRLR expression profiles of PCI-6A and PCI-6B cells might be because of culture selection, we evaluated PRLR expression in sections of the primary tumour and the metachronously developed lymph node metastasis by immunohistochemistry." (PMID 21505459, 2011). "The majority of PCI-6A cells, which had been generated from a primary tumour, were highly PRLR positive, whereas all PCI-6B cells generated from a metachronously developed corresponding lymph node metastasis were negative for PRLR, both on the cell surface and in the cytoplasm." (PMID 21505459, 2011).
mastitis (2 papers, 2025). Inflammation of breast tissue during lactation or postpartum due to an obstructed duct or infection. "Levels of IFN-γ, IL-4, TNF-α, MYD88, CCL5, TLR4, TLR9, LTF, PRLR, Keap1 and OXSR1 genes expression were significantly up-regulated in ewes affected with mastitis than resistant ones." (PMID 40542007, 2025). "Mastitis-affected ewes had considerably higher levels of IFN-γ, IL-4, TNF-α, MYD88, CCL5, TLR4, TLR9, LTF, and PRLR gene expression than resistant ones." (PMID 40542007, 2025). "In the current investigation, qRT-PCR was used to measure the levels of antioxidant (CAT, GPX1, Keap1, OXSR1, ATOX1, GST, and Nrf2) and immune (IFN-γ, IL-4, TNF-α, MYD88, CCL5, TLR4, TLR9, LTF, and PRLR) genes in Barki ewes that were resistant and non-resistant to mastitis." (PMID 40542007, 2025).
ovarian tumors (2 papers, 2020 to 2025). "Extensive expression of PRLR was detected in all examined ovarian tumor tissue specimens except for one from a patient who had focal expression of PRLR and this patient was HCMV-negative in her tumor." (PMID 32121009, 2020). "Additionally, ovarian tumours exhibit high levels of prolactin receptor (PRLR)." (PMID 41463341, 2025). "As extensive expression of PRLR was found in HCMV-infected ovarian tumors, and the PRL/PRLR axis can promote tumor growth, this may provide yet another mechanism by which HCMV can promote disease progression of cancer." (PMID 32121009, 2020). "Extensive expression of PRLR was detected in all examined ovarian tumor tissues except in the only patient who was negative for HCMV." (PMID 32121009, 2020).
psoriatic arthritis (2 papers, 2017 to 2023). Joint inflammation associated with psoriasis. "Psoriatic arthritis (PsA) is also an autoinflammatory disease, in which the prolactin receptor is also expressed in macrophages." (PMID 28690611, 2017). "For example, in rheumatoid arthritis and psoriatic arthritis, PRL can be locally produced by macrophages, T cells and synovial fibroblasts while PRLR is expressed in synovial macrophages, lymphocytes, and fibroblasts." (PMID 37490712, 2023).
sarcoma (2 papers, 2016 to 2026). A usually aggressive malignant neoplasm of the soft tissue or bone. "PRL can activate the JAK-STAT signalling pathway by binding to PRLR on sarcoma cells, leading to the up-regulation of c-MYC." (PMID 42083506, 2026). "In this study, we show that PrlR levels are increased in a mouse sarcoma cell line treated with TSC2 siRNA." (PMID 26765535, 2016).
steatosis (2 papers, 2020 to 2022). Increased lipid within the cytoplasm of cells. "They believed that there is a new link between the central nervous system and the liver, and PRL improves steatosis of the liver through PRLR and fat/CD36." (PMID 32477263, 2020).
acinar adenocarcinoma of the prostate (1 paper, 2010). "Recent evidence has shown that the PRLR was overexpressed in ductal vs acinar adenocarcinoma of the prostate at both the transcript and the protein level." (PMID 21144038, 2010).
acinar carcinoma (1 paper, 2010). "PRLR transcripts identified from microdissected cell populations were elevated 6-fold in ductal vs. acinar carcinoma cells." (PMID 21144038, 2010).
adenosis (1 paper, 2008). "In contrast, normal epithelium, along with usual ductal hyperplasia and microglandular adenosis, generally showed only minimal detectable PRLR, present as the luminal surface labeling of occasional cells." (PMID 21655368, 2008).
amyotrophic lateral sclerosis (1 paper, 2014). Amyotrophic lateral sclerosis (ALS) is a neurodegenerative disease characterized by progressive muscular paralysis reflecting degeneration of motor neurons in the primary motor cortex, corticospinal tracts, brainstem and spinal cord. "The most downregulated gene was BMPER, an inhibitor of BMP (-10 fold) followed by NIF3LBP1 (-7.4 fold), which binds NIF3 (an amyotrophic lateral sclerosis candidate gene), MCC1 (-7.4 fold) (a tumor suppressor), and PRLR (-4.2) (a prolactin receptor important for decidua function)." (PMID 26085845, 2014).
benign breast disease (1 paper, 2023). "To date, two common germline PRLR variants are reported to demonstrate constitutive activity, with one, Ile146Leu, overrepresented in benign breast disease, while a rare activating variant, Asn492Ile, is reported to be associated with an increased incidence of prolactinoma." (PMID 36445946, 2023).
bone tumors (1 paper, 2016). "Therefore, although the prolactin pathway is active in both SSM2 and SSM3 bone tumors, PrlR signaling is not sufficient to mediate the growth of ERα+/PR+ SSM3 cells in bones in the absence of ovarian hormones." (PMID 27391074, 2016).
brain tumor (1 paper, 2016). "Expression of Prolactin receptor (PrlR) was detected at high levels in U251-MG, at low levels in U87-MG and barely detectable in U373 cell lines and in 66% of brain tumor tissues from 32 GBM patients by immunohistochemical technique." (PMID 27788487, 2016).
cervical squamous cell carcinoma (1 paper, 2021). A squamous cell carcinoma arising from the cervical epithelium. "The expression of PRLR in most cancer tissues was significantly lower than that in paracancerous tissues, including ccRCC, cervical squamous cell carcinoma, endocervical adenocarcinoma, and uterine corpus endometrial carcinoma." (PMID 34539753, 2021).
endometrial tumors (1 paper, 2014). "Circulating levels of prolactin, a polypeptide hormone involved in numerous physiological processes including reproduction, are higher among EC patients compared to healthy controls, and increased PRLR expression has been noted for endometrial tumors compared to non-cancerous endometrial tissue." (PMID 24096698, 2014).
endometritis (1 paper, 2024). An acute or chronic, usually bacterial infectious process affecting the endometrium. "The levels of the PRLR, LTF, CLA-DRB3.2, beta defensin, TLR2, TLR4, and CCL5 genes were significantly up-regulated in postparturient goats with endometritis compared to tolerant ones, while the GPX4, GST, SOD3, CAT, and ATOX1 gene patterns demonstrated the opposite tendency." (PMID 39195794, 2024).
Follicular Cyst (1 paper, 2023). Cyst due to the occlusion of the duct of a follicle or small gland. "We compared transcriptomic data from follicular cysts to the reference genome and identified non-synonymous mutations in three genes: IBSP, LDHB and PRLR." (PMID 38274662, 2023). "These genes are involved in several pathways involved in follicular cyst formation: ECM-receptor interaction (IBSP), PI3K-Akt signaling pathway (IBSP and PRLR) and metabolic pathways (LDHB)." (PMID 38274662, 2023).
hypercortisolemia (1 paper, 2022). "The modulation of hormonal receptors, i.e., ESR1 and PRLR, in response to treatment further highlighted the multifactorial effects of prolonged hypercortisolemia in visceral adipose tissue function." (PMID 35737302, 2022). "Finally, whereas the availability of ESR1 was decreased in hypercortisolemia, prolactin receptor (PRLR) availability was increased." (PMID 35737302, 2022).
Hypocalcemia (1 paper, 2012). An abnormally decreased calcium concentration in the blood. "These authors also demonstrated that circulating PRL causes prolactin receptor expression in the hypothalamus, suggesting a preventive role against stress-induced hypocalcemia and ulcerogenesis." (PMID 22291890, 2012).
inflammatory skin disorders (1 paper, 2013). "The current serum-free human skin organ culture model permits one to investigate whether the regulation of PRL and/or PRLR is altered in inflammatory skin disorders, for example in psoriasis." (PMID 23626671, 2013).
laryngeal carcinoma (1 paper, 2025). Carcinoma that arises from the laryngeal epithelium. "were the first to report the co-expression of prolactin receptor (PRLR) and estrogen receptor (ER) in laryngeal cancer cells." (PMID 40823098, 2025).
leukemia (1 paper, 2023). A malignant (clonal) hematologic disorder, involving hematopoietic stem cells and characterized by the presence of primitive or atypical myeloid or lymphoid cells in the bone marrow and the blood. "Disruption of the PRLR signaling, either using a mutant PRL or a dominant-negative isoform of PRLR, reduced the leukemia burden in vivo, in xenotransplantation assays." (PMID 37208719, 2023). "Interestingly, the migration capacity to peripheral organs of both PRL mut- and PRLR short-expressing AML cells was severely diminished, as observed in the leukemia levels in spleen." (PMID 37208719, 2023).
lobular carcinoma (1 paper, 2010). "To facilitate these studies we developed and characterized PRLR isoform specific polyclonal antibodies that reveal that three isoforms, LF, SF1a and SF1b, are differentially expressed in ductal and lobular carcinoma tissues." (PMID 21144038, 2010).
measles (1 paper, 2025). A highly contagious viral infection caused by the measles virus. "Some hormone receptors are used by viruses to facilitate cell entry, and although this has not been shown for GH, prolactin, or their receptors, it is notable that the protein nectin-4, which interacts with the prolactin receptor, is used in this way by some viruses, including measles." (PMID 40105703, 2025).
Miscarriage (1 paper, 2023). A pregnancy that ends at a stage in which the fetus is incapable of surviving on its own, defined as the spontaneous loss of a fetus before the 22th week of pregnancy. "Our study found that SGK1 and its signaling pathway-related proteins (p-Nedd4-2, 14–3-3 protein, ENaC-α), estrogen and progesterone and their receptors (E2, P, ERβ, PR), and decidualization markers (PRL, PRLR, IGFBP-1) were expressed at lower levels in unexplained recurrent miscarriage tissue." (PMID 37280474, 2023).
myelodysplastic syndrome (1 paper, 2023). A clonal hematopoietic disorder characterized by dysplasia and ineffective hematopoiesis in one or more of the hematopoietic cell lines. "Interestingly, not only AML, but also the AML-related myeloid neoplasia Myelodysplastic syndromes (MDS) overexpress PRLR on the cell surface, observing a wide range of expression levels, at a comparable frequency rate (AML: 32.278 ± 3.591%; MDS: 32.947 ± 3.708%)." (PMID 37208719, 2023).
myeloma (1 paper, 2014). "Although PRL has been shown to be proapoptotic in other tissues or cell types (e.g. keratinocytes, chondrocyte, human myeloma-derived cell lines), the apoptotic signaling mechanism has not been described so far for PRLR." (PMID 24859278, 2014).
pancreatic ductal adenocarcinoma (1 paper, 2021). An infiltrating adenocarcinoma that arises from the epithelial cells of the pancreas. "Here, we reveal the role and underlying mechanism of PRLR-SF in pancreatic ductal adenocarcinoma (PDAC)." (PMID 33664869, 2021).
parathyroid tumours (1 paper, 2012). "As menin is a known primary affected tumour suppressor in parathyroid tumours, it is possible that its dysfunction would cause a disinhibition of GSK3β mediated degradation of PRLr, hence stabilizing the long/ΔS1 isoforms." (PMID 22606260, 2012). "In parathyroid tumours, PRLr immunoreactivity was observed in the cytoplasm (in all cases, n = 36), cytoplasmic granulae (n = 16), the plasma membrane (n = 12) or enlarged lysosomes (n = 4)." (PMID 22606260, 2012). "PRLR-total expression was observed in 35/37 parathyroid tumours, at levels that are higher (>1.5, n = 7), lower (<0.5; n = 9) or comparable (>0.5 and <1.5; n = 19) to the mean level for the normal parathyroids (0.77–1.30)." (PMID 22606260, 2012). "Comparison of the prolactin receptor gene expression with clinical characteristics of the 37 parathyroid tumour cases revealed several significant relationships." (PMID 22606260, 2012). "The PRLr expression pattern located to cytoplasm and granulae uniformly observed in normal rim was partly changed in parathyroid tumours." (PMID 22606260, 2012). "Expression of PRLR gene transcripts was determined by qRT-PCR analyses of parathyroid tumours and normal tissues." (PMID 22606260, 2012). "PRLr expression was investigated in a panel of 37 patients with sporadic parathyroid tumours and its functionality in cultured parathyroid tumour cells." (PMID 22606260, 2012). "We determined PRLR gene and PRLr isoform expression in parathyroid tumours and normal tissues, and evaluated parathyroid tumour cell function and expression profiles upon prolactin stimulation in vitro." (PMID 22606260, 2012). "Given the frequent occurrence of PHPT in women and the role of PRLr in other tumours we aimed to assess PRLr expression and functionality in human parathyroid tumours." (PMID 22606260, 2012). "In conclusion, we demonstrate high abundance of the prolactin receptor in the human parathyroid gland, aberrant subcellular localisation in parathyroid tumours, and varying levels of PRLr isoforms." (PMID 22606260, 2012). "Overall, the immunohistochemical results support our Western blot data suggesting that PRLr is expressed in the vast majority of all parathyroid tumours investigated." (PMID 22606260, 2012). "We demonstrate that the prolactin receptor is highly abundant in human parathyroid tissues and that PRLr isoforms expression and PRLr subcellular localisation are altered in parathyroid tumours." (PMID 22606260, 2012). "The 60/70 kDa PRLr product was expressed in all 37 parathyroid tumours." (PMID 22606260, 2012). "Moreover, PRLR gene expression in parathyroid tumours was inversely correlated with the patients’ plasma calcium levels." (PMID 22606260, 2012). "PRLr products of 60/70 kDa were highly expressed in all parathyroid tumours." (PMID 22606260, 2012). "Since no previous data regarding gene expression profiling and coupling to the PRLr in parathyroid tumours is known to be present, a direct comparison of our findings with independent observations could not be made." (PMID 22606260, 2012). "In this study we demonstrate high abundance of the prolactin receptor in parathyroid tissues, correlation of its expression levels to clinical characteristics, as well as localization and functional responses upon prolactin stimulation in parathyroid tumour cells." (PMID 22606260, 2012). "Hence the variation in PRLR observed in parathyroid tumours was not evidently related to the alteration of single transcripts." (PMID 22606260, 2012).
periodontitis (1 paper, 2023). An acute or chronic inflammatory process that affects the tissues that surround and support the teeth. "These mice with periodontitis were divided to control groups and the groups with infusion of mandibular BM-MSCs after targeted inhibition of miR-181a-5p or overexpression of PRLR." (PMID 37490712, 2023). "On the contrary, PRLR appeared to be an anti-inflammatory factor in our experimental settings, since a lower expression level of PRLR was observed in mandibular BM-MSCs derived from periodontitis mice than that from normal mice." (PMID 37490712, 2023). "Furthermore, BM-MSCs with miR-181a-5p inhibition or PRLR-overexpression showed enhanced in vivo immunosuppressive properties in the periodontitis mouse model." (PMID 37490712, 2023). "Periodontitis-associated changes in gene expressions, including downregulated expressions of LncRNA SPIRE1 or PRLR, and increased miR-181a-5p expression, resulted in significantly activated JAK/STAT3 signaling in normal BM-MSCs, in comparison to the transfected control cells." (PMID 37490712, 2023). "In addition, PRLR was also overexpressed to further confirm its role in the periodontitis development." (PMID 37490712, 2023). "Furthermore, mandibular BM-MSCs from mice with periodontitis showed significantly down-regulated expressions of PRLR mRNA and protein, as evidenced by qPCR and western blot assays, respectively." (PMID 37490712, 2023). "To further evaluate the in vivo benefits of targeted regulation of the LncRNA SPIRE1/miR-181a-5p/PRLR axis in immune modulation, we investigated the immunosuppressive properties of mandibular BM-MSCs after gene manipulations in LPS-induced experimental periodontitis mouse model." (PMID 37490712, 2023). "Notably, targeted knockdown of LncRNA SPIRE1 or PRLR or transfection of miR-181a-5p mimics activated the JAK/STAT3 signaling in normal BM-MSCs, while treatment with STAT3 inhibitor C188-9 restored the immunomodulatory properties of periodontitis-associated BM-MSCs." (PMID 37490712, 2023).
polycystic ovarian syndrome (1 paper, 2023). "The PRLR gene can potentially be implicated in the risk of polycystic ovarian syndrome (PCOS), which is a common condition characterized by anovulation, hyperandrogenism, insulin resistance, and polycystic ovaries." (PMID 37993904, 2023). "The prolactin receptor gene (PRLR) may contribute to polycystic ovarian syndrome (PCOS) since it plays important roles in physiological ovarian functions." (PMID 37993904, 2023).
preeclampsia (1 paper, 2024). Preeclampsia is a hypertensive disorder of pregnancy that is characterized by new-onset hypertension with proteinuria presenting after 20 weeks of gestation, and depending on mild or severe forms may initially present with severe headache, visual disturbances, and hyperreflexia. "These include decidualization markers such as PRLR and IGFBP3, as well as genes that have previously been reported to have roles in trophoblast invasion, such as FERMT2 and RORB, for which expression changes in preeclampsia have been observed in fetal placenta." (PMID 39090334, 2024).